NHSL3 (NHS like 3)
Description:
Able to directly activate the TNF-NFkappaB signaling pathway.
Synonyms: KIAA1522
Tractability: Antibody: the Human Protein Atlas places it where antibodies can reach.
Gene: Protein-coding gene on chromosome 1 (32,741,696 to 32,774,970, forward strand). Ensembl gene ENSG00000162522.
Subcellular location (Human Protein Atlas): Cell Junctions; Plasma membrane; Nucleoplasm
Gene Ontology:
Molecular function: protein binding
Biological process: cell differentiation
Cellular component: cell junction; plasma membrane
Genetic constraint (gnomAD): Loss-of-function variants: 34 observed, 58.88 expected, observed/expected ratio (o/e) 0.58, 90% interval 0.44 to 0.77. The upper end of that interval is the gene's LOEUF score, 0.77, which puts it in group 3 of 6, group 1 being the genes least tolerant of losing a copy. Missense variants: 1,453 observed, 1,352.7 expected, observed/expected ratio (o/e) 1.07, 90% interval 1.03 to 1.12. Synonymous variants: 652 observed, 573.79 expected, observed/expected ratio (o/e) 1.14, 90% interval 1.07 to 1.21.
Homologues: Orthologues: chimpanzee NHSL3 (99% identical), macaque NHSL3 (91% identical), pig NHSL3 (87% identical), dog NHSL3 (86% identical), rat Nhsl3 (82% identical), mouse Nhsl3 (81% identical), guinea pig NHSL3 (78% identical), tropical clawed frog nhsl3 (32% identical), zebrafish nhsl3 (31% identical). Paralogues in human: NHSL1 (20% identical), NHS (17% identical), NHSL2 (14% identical).
Diseases named in the same sentence as NHSL3 in open-access papers:
NHSL3 is named in the same sentence as 25 diseases in open-access papers, as found by Europe PMC text mining. Sharing a sentence is not in itself a finding about the gene and the disease. The quoted sentences say what the papers report.
Nance-Horan syndrome (1 paper, 2025). A syndrome characterized by the association in male patients of congenital cataracts with microcornea, dental anomalies and facial dysmorphism. "Here, we show that knock-out cells for NHSL3, the most recently identified member of the Nance-Horan Syndrome family, are more persistent than parental cells in single cell migration, but that, in wound healing, follower cells are impaired in their ability to follow leader cells." (PMID 39747206, 2025). "NHSL3 is the most recently identified gene of the Nance-Horan syndrome family." (PMID 39747206, 2025).
NHSL3 also shares sentences with these, for which no sentence is quoted: breast carcinoma (13 papers); tumor (13); cancer (9); hepatocellular carcinoma (6); lung cancer (6); esophageal squamous cell carcinoma (4); non-small cell lung carcinoma (4); squamous cell carcinoma (3); adenocarcinoma (2); colorectal cancer (2); esophageal cancer (2); lung adenocarcinoma (2); triple-negative breast carcinoma (2); basal cell carcinoma (1); colon cancer (1); gallbladder cancer (1); gastrointestinal tumors (1); laryngeal squamous cell carcinoma (1); lung adenocarcinoma in situ (1); multiple myeloma (1); osteosarcoma (1); pancreatic cancer (1); pericardial effusion (1); prostate carcinoma (1).